TNFRSF13B (TNF receptor superfamily member 13B)
Diseases named in the same sentence as TNFRSF13B in open-access papers (continued):
Sharing a sentence is not in itself a finding about the gene and the disease.
COVID-19 (8 papers, 2021 to 2024). A disease caused by infection with severe acute respiratory syndrome coronavirus 2. "Pathogenic variants in the TNFRSF13B were also previously identified in isolated cases of patients with severe COVID-19." (PMID 39062917, 2024). "Of these, one homozygous variant in the genes TBK1 and TNFRSF13B, respectively were considered likely causal factors for the severe COVID-19 disease course observed in the present case." (PMID 34210994, 2021). "In particular, mutations in TNFRSF13B, UBA1, IRF2BP2, and FCN3 were already reported to be associated with severe COVID-19." (PMID 36552859, 2022). "Patients with mild COVID-19 displayed a marked interaction between neutrophil and plasmablasts through BAFF (TNFSF13B) and BAFF receptors (encoded by TNFRSF13C, TNFRSF13B, or TNFRSF17)." (PMID 34548411, 2021). "We suggest that high production of TNF, TNFRSF13B, and IL32 might be associated with and serve as markers for COVID-19 severity-specific therapies." (PMID 35983322, 2022). "We suggested that high production of TNF, TNFRSF13B, and IL32 might be associated with and can serve as markers for COVID-19 severity." (PMID 35983322, 2022).
antibody deficiency syndrome (6 papers, 2014 to 2025). "Variants in the gene TNFRSF13B have been associated with the common variable immunodeficiency (CVID) syndrome “Common variable immune deficiency 2” (CVID2, OMIM # 240500), and the immunoglobulin A deficiency (IGAD) “Immunoglobulin A deficiency 2”/IGAD2 (OMIM # 609529)." (PMID 34210994, 2021).
chronic lymphocytic leukemia (6 papers, 2009 to 2025). "It has also been reported that several genetic variants in TNFRSF13B influence gene expression and susceptibility to chronic lymphocytic leukaemia." (PMID 35524261, 2022). "The soluble form of TNFRSF13B can be detected in blood and is found to be elevated in patients with chronic lymphocytic leukaemia." (PMID 35524261, 2022).
IgA deficiency (5 papers, 2016 to 2025). "For instance, the rare missense variant in TNFRSF13B (rs72553883) causing common variable immunodeficiency and selective immunoglobulin A deficiency was associated with platelet, myeloid white cell and lymphoid white cell indices." (PMID 27863252, 2016). "Common genetic variation in TNFRSF13B locus was previously associated with different levels of immunoglobulins in serum, while rare deleterious variants were implicated in common variable immunodeficiencies and IgA deficiencies." (PMID 38149987, 2023). "Collectively, these observations suggest that mutations in TNFRSF13B could induce CVID and IgA deficiency." (PMID 33981304, 2021). "Furthermore, several genetic abnormalities have already been found in the TNFRSF13B gene in some individuals with CVID and IgA deficiency, pointing to a role of TNFRSF13B in the development of IgA deficiency (and CVID) in some individuals." (PMID 33981304, 2021).
inflammatory bowel disease (4 papers, 2021 to 2024). A spectrum of small and large bowel inflammatory diseases of unknown etiology. "Patient 84 had a mutation of TNFRSF13B inherited from his mother, who was diagnosed with inflammatory bowel disease(IBD)." (PMID 38547930, 2024). "In dogs suffering from inflammatory bowel disease (IBD) associated with significantly decreased levels of IgA, the expression levels of IgA were associated with the DNA methylation state of the TNFRSF13B and TNFRSF13C genes and the mRNA expression levels of TACI and BAFF-R." (PMID 33981304, 2021).
viral infections (4 papers, 2021 to 2025). "At the same time, certain monogenic causes of the CVID phenotype (e.g., NFKB1, NFKB2, TNFSF12/TWEAK/, TNFRSF13B/TACI/, or IKZF1/IKAROS/) have been reported to cause severe viral infections individually." (PMID 41229388, 2025). "Besides, genetic defects in some molecules that interact with T cells (such as NFKB1, NFKB2, and TNFRSF13B) in patients diagnosed with CVID can also lead to critical viral diseases." (PMID 40442532, 2025).
asthma (3 papers, 2014 to 2023). "Mutations in the TNFRSF13B gene have been found in CVID patients and are also associated with an increased risk of asthma development." (PMID 34575269, 2021). "In addition, posterior probability was >20% between the CDTA locus 17p11.2 (TNFRSF13B) and non-suppurative otitis media, and the NP locus 9p24.1 (IL33) and asthma." (PMID 36653354, 2023).
sarcoidosis (3 papers, 2013 to 2021). Sarcoidosis is a multisystemic disorder of unknown cause characterized by the formation of immune granulomas in involved organs. "Two patients with TH without infectious cause (incidence 10.5%) and 2 patients with sarcoidosis (incidence 2.8%) displayed TNFRSF13B/TACI alterations, all in heterozygous state." (PMID 23956760, 2013). "We also identified patients with sarcoidosis carrying heterozygous alterations of TNFRSF13B/TACI, but their total frequency (2.8%) was rather low and rather similar to that observed in several healthy control groups." (PMID 23956760, 2013). "Furthermore, we observed that both a patient with sarcoidosis and her healthy grandson carried a heterozygous alteration of TNFRSF13B/TACI (R202H) and displayed sIgG4D." (PMID 23956760, 2013). "Considering that the number of sarcoidosis patients displaying TNFRSF13B/TACI defects in our study was small, the contribution of TACI to disease activity through a defective BAFF signaling is still elusive and remains to be determined." (PMID 23956760, 2013). "The aim of this study was to investigate the role of TNFRSF13B/TACI alterations in the pathogenesis of two common benign lymphoproliferative disorders, namely, sarcoidosis and tonsillar hypertrophy." (PMID 23956760, 2013). "Our purpose was to investigate the role of TNFRSF13B/TACI defects in the pathogenesis of two common lymphoproliferative disorders, namely, sarcoidosis and tonsillar hypertrophy (TH)." (PMID 23956760, 2013).
Epstein-Barr virus infection (2 papers, 2024). An infection that is caused by Epstein-Barr virus. "We found one pathogenic variant in the NFKB1 gene in a father and his daughter, one pathogenic variant in the TNFRSF13B gene, and one pathogenic variant in the MAGT1 gene associated with X-linked immunodeficiency with magnesium defect, Epstein-Barr virus infection, and neoplasia (XMEN syndrome)." (PMID 38406025, 2024).
lymphoproliferative disorders (2 papers, 2013 to 2025). "However, the contribution of TNFRSF13B/TACI alterations in the pathogenesis of human lymphoproliferative disorders, malignant or benign, is elusive." (PMID 23956760, 2013).
melanoma (2 papers, 2019 to 2021). A malignant, usually aggressive tumor composed of atypical, neoplastic melanocytes. "A number of identified molecules including TNFRSF13B, LAG3, NRP1, ENTPD1, NT5E, CCL21, and CCR7 can serve as future therapeutic targets in melanoma treatment." (PMID 34159752, 2021). "A number of identified molecules, including TNFRSF13B, LAG3, NRP1, ENTPD1, NT5E, CCL21, and CCR7, can serve as future therapeutic targets in the treatment of melanoma." (PMID 34159752, 2021).
neutropenia (2 papers, 2021 to 2022). A decrease in the number of neutrophils found in the blood. "In fact, though the ELANE mutation alone, unreported in the GnomAD database thus far, can explain the cyclic neutropenia of this patient, we cannot exclude that TNFRSF13B, present with a variant showing no homozygotes in the same database, may also be involved in the clinical phenotype." (PMID 34573280, 2021).
Obesity (2 papers, 2021 to 2022). Accumulation of substantial excess body fat. "Regarding the association between TNFRSF13B, TNFRSF10A, and type II diabetes mellitus, our results support previous findings of TNF-α being linked to obesity and insulin resistance." (PMID 35211520, 2022).
prostate carcinoma (2 papers, 2022 to 2026). A carcinoma that arises from epithelial cells of the prostate gland. "In this study, TNFRSF13B rs4792800, an intronic variant, was found to be a significant variant associated with prostate cancer recurrence." (PMID 35524261, 2022). "In line with our study, TNFRSF13B knockdown significantly decreased the colony growth of 22Rv1 and PC-3 human prostate cancer cells, suggesting the potential role of TNFRSF13B in prostate cancer progression." (PMID 35524261, 2022). "The present study suggests the potential role of immunodeficiency pathway-related genes, primarily TNFRSF13B, in prostate cancer progression." (PMID 35524261, 2022). "Increased TNFRSF13B expression suggested poor prognosis in four independent prostate cancer datasets." (PMID 35524261, 2022). "Further investigations revealed that silencing TNFRSF13B gene reduced colony formation in two prostate cancer cell lines, suggesting a possible role for TNFRSF13B in prostate cancer pathogenesis." (PMID 35524261, 2022). "In the multivariate Cox model, after adjustment for clinicopathological predictors, TNFRSF13B rs4792800 was independently associated with BCR (HR = 1.78, 95% CI = 1.16–2.71, p = 0.008), reinforcing the importance of TNFRSF13B rs4792800 in prostate cancer progression." (PMID 35524261, 2022). "Furthermore, the TNFRSF13B was knocked down in 22Rv1 and PC-3 human prostate cancer cell lines via transfecting short hairpin RNAs and cell proliferation and colony formation assays were performed." (PMID 35524261, 2022). "Collectively, these results suggest that silencing TNFRSF13B might inhibit tumorigenesis through modulating prostate cancer cell colony formation." (PMID 35524261, 2022). "Although the link between TNFRSF13B expression and prostate cancer remains unknown, gene expression analysis based on public datasets showed that TNFRSF13B overexpression correlated with poor prognosis in patients with prostate cancer." (PMID 35524261, 2022).
autoinflammatory syndrome (1 paper, 2025). A group of disorders of the innate immune system characterized by attacks of seemingly unprovoked inflammation without significant levels of either autoantibodies or autoreactive T cells more characteristic of autoimmune disease. "A genetic panel (Invitae, GeneMetrics) targeting autoinflammatory syndromes did not identify known pathogenic variants but revealed a heterozygous variant in TNFRSF13B, associated with CVID." (PMID 40995171, 2025).
avian influenza (1 paper, 2020). Infection of domestic and wild fowl and other birds with influenza A virus. "One receptor for TNFSF13B, TNFRSF13B, was among the genes significant in the trachea challenge by line interaction at 6 dpi and was differentially expressed between the Fayoumi and Leghorn chickens in the lung in both non-challenged birds and birds challenged with avian influenza." (PMID 32117434, 2020).
epilepsy (1 paper, 2021). A brain disorder characterized by episodes of abnormally increased neuronal discharge resulting in transient episodes of sensory or motor neurological dysfunction, or psychic dysfunction. "There was heterogeneity regarding causative genes (n = 754) with some of the most common ones being COL2A1 (n = 12; skeletal dysplasia), SCN1A (n = 8; epilepsy), and TNFRSF13B (n = 4; inborn errors of immunity)." (PMID 33726816, 2021).
myeloid malignancy (1 paper, 2025). "P/LP likely germline variants in genes that have previously been associated with adult myeloid malignancy were found in 16 patients (4.4%), including ATM, BRCA2, CHEK2, and TNFRSF13B." (PMID 40766138, 2025).
renal cell carcinoma (1 paper, 2020). "Renal cell carcinoma has a good effect on immunotherapy (29120911), so we inquired about the relationship between TNFRSF13B and six kinds of immune cells." (PMID 32655996, 2020).
seminoma (1 paper, 2024). A radiosensitive malignant germ cell tumor found in the testis (especially undescended), and extragonadal sites (anterior mediastinum and pineal gland). "In the tumor microenvironment of non-metastatic non-seminomas, TNFSF13B was highly expressed on FDC, cDC1 and cDC2 and promoted the proliferation through the receptors TNFRSF13B and TNFRSF17." (PMID 39528470, 2024).
Sjögren’s syndrome (1 paper, 2023). "There are strong shared pathologies between Sjögren’s syndrome and CVID and we therefore postulate that both mother and child have variable presentations of CVID associated with this pathogenic TNFRSF13B variant." (PMID 38006337, 2023).
sterile (1 paper, 2025). "Future studies are needed to evaluate if TNFRSF13B variants may contribute to a broader spectrum of sterile inflammatory diseases, particularly in genetically predisposed individuals with atypical acneiform presentations." (PMID 40995171, 2025).
Thrombocytopenia (1 paper, 2020). A reduction in the number of circulating thrombocytes. "A p.Ser144Leu mutation in TNFRSF13B was found by testing DNA from nucleated cells of the patient's blood, suggesting the possibility of thrombocytopenia." (PMID 32991402, 2020). "Thrombocytopenia may be associated with mutated TNFRSF13B gene." (PMID 32991402, 2020).
thymoma (1 paper, 2022). A neoplasm arising from the epithelial cells of the thymus. "FAM46C expression was found to be positively correlated with TNFRSF17 and TNFRSF13B, except in DLBC, thymoma (THYM) and UCS." (PMID 35222533, 2022).
X-linked lymphoproliferative syndrome (1 paper, 2024). X-linked lymphoproliferative disease is a hereditary immunodeficiency characterized, in the majority of cases, by an inadequate immune response to infection with the Epstein-Barr virus (EBV). "A total of 17 patients (15.7 %) harbored IEI-associated mutations, including 4 cases with X-linked lymphoproliferative syndrome (XLP), 3 cases had mutations in tumor necrosis factor receptor superfamily 13B (TNFRSF13B), 2 cases with Activated p110 syndrome (APDS)." (PMID 38547930, 2024).
tumor (42 papers, 2009 to 2025). "Subsequently, activated HSCs (α-HSCs) secrete TNFSF13, which recruits and promotes tumor progression through the TNFSF13/TNFRSF13B axis." (PMID 39979806, 2025). "The mRNA level of CR2, INSL4, FGF5, RAET1L and TNFRSF13B was upregulated in LUAD tumor tissues compared with paired normal tissues whereas AGER was downregulated." (PMID 36294477, 2022). "The expression of GNG8, MYO1H, and TNFRSF13B was significantly down-regulated, while the expression of SYT14 and FOXA2 was significantly up-regulated in the samples with higher tumor stage, the samples with high risk had lower overall survival rates." (PMID 34322156, 2021). "There was a high positive correlation between TNFRSF13B and ESTIMATE score, indicating that the more TNFRSF13B expression, the less the content of tumor cells, the more the content of immune cells and stromal cells." (PMID 32655996, 2020). "The expression of TNFRSF13B is positively correlated with tumor stage and grade." (PMID 32655996, 2020). "TNFRSF13B is an essential factor in the tumor microenvironment of KIRC." (PMID 32655996, 2020). "In contrast, the activity of pathways from macrophages, such as VEGFB to VEGFR1 and TNFSF13B to TNFRSF13B, was reduced in tumors, possibly reflecting adaptive changes in macrophage function under tumor conditions, which could impact immune responses and tumor cell regulation (right)." (PMID 39850883, 2024). "Simultaneously, SPP1 downregulated CD40LG, TNFSF15, TNFRSF13B, IL6R, KLRK1, and other immune stimulants, indicating that SPP1 played a role in the evasion of tumor immunity by controlling the immunosuppressive surroundings." (PMID 38329443, 2024). "Moreover, the expression of GNG8, MYO1H, and TNFRSF13B was significantly down-regulated, while the expression of SYT14 and FOXA2 was significantly up-regulated in the samples with higher tumor stage." (PMID 34322156, 2021). "Others, such as TNFRSF13B (member of the superfamily of TNF receptors) and ADAM6 (a member of the family of A disintegrin and metalloproteases) and contribute to a huge variety of biological processes such as cell growth, cell differentiation and metabolism and can participate in tumor promotion." (PMID 35990685, 2022).
cancer (20 papers, 2009 to 2025). A tumor composed of atypical neoplastic, often pleomorphic cells that invade other tissues. "To date, several studies have reported significant associations between genetic polymorphisms in TNFRSF13B and the risks of several types of cancer." (PMID 35524261, 2022). "TNFRSF13B, a member of the TNF receptor superfamily, which occupied an important position in the proliferation and progression of cancer cell." (PMID 33588862, 2021). "Among those genes, we focused on KCNA2, TNFRSF13B and ADAM6, which exhibit a 11x, 7x and 3.5x fold increase respectively, since they were among the 9 differential expressed genes with p values <0.00001 that have a clearer biological role in cancer." (PMID 35990685, 2022). "An intestinal immune network for IgA production might provide new markers in enteric DLBCL, such as CCR10, TNFRSF13B, AICDA, and HLA-DOB, as well as genes involved in transcriptional misregulation in cancer (NFKBIZ, FUT8, LMO2, CCND2, BCL2A1, ETV6, and CDK14)." (PMID 29992138, 2018).
infection (17 papers, 2007 to 2025). The state of being infected such as from the introduction of a foreign agent such as serum, vaccine, antigenic substance or organism. "Results show that several rare pathogenic/likely pathogenic genomic variants in genes CFTR, MASP2, MEFV, TNFRSF13B, and RNASEL likely contribute to the severe infection outcomes in our patient cohort." (PMID 39062917, 2024). "WT or Tnfrsf13b mutant mice were infected with C. rodentium (founder mice), and cohoused mice were tested for infection 7 days later." (PMID 34111031, 2021). "WT mice also produced significantly more intimin-specific IgA than Tnfrsf13b mutant mice 21 days after infection." (PMID 34111031, 2021). "A total of 6 of 8 WT and only 2 of 30 Tnfrsf13b mutant mice had IgM specific for C. rodentium in blood 7 days after infection." (PMID 34111031, 2021). "Thus, A144E heterozygous mice, obtained by crossing WT mice with homozygous Tnfrsf13b A144E mice, frequently resist infection or produce 20-fold less CFUs than WT littermates, and Tnfrsf13b A144E/A144E and Tnfrsf13b-KO mice, produced and backcrossed to C57BL/6 independently, are resistant." (PMID 34111031, 2021). "Analysis of cell-cell interactions between neutrophils and PCs showed that during infection, the latter downregulate key survival receptors such as BCMA (Tnfrsf17) and TACI (Tnfrsf13b)." (PMID 37669943, 2023).
blood cancers (1 paper, 2024). "Among the proteins associated with risk of haematological cancers, we identified associations with risk of multiple blood cancers for members of the FC-receptor protein [FCRL1, FCRL2, FCRL3, FCRL5, FCRLB] and TNF receptor families [TNFRSF4, TNFRSF9, TNFRSF13B, TNFRSF13C, TNFSF13B, TNFSF13]." (PMID 38750076, 2024).